PDZRN3 (PDZ domain containing ring finger 3)
Description:
E3 ubiquitin-protein ligase. Plays an important role in regulating the surface level of MUSK on myotubes. Mediates the ubiquitination of MUSK, promoting its endocytosis and lysosomal degradation. Might contribute to terminal myogenic differentiation.
Synonyms: KIAA1095; LNX3; SEMCAP3; SEMACAP3
Tractability: PROTAC: UniProt records ubiquitination sites on it; its protein half-life has been measured.
Gene: Protein-coding gene on chromosome 3 (73,382,431 to 73,624,941, reverse strand). Ensembl gene ENSG00000121440.
Subcellular location: Synapse; Cytoplasm
Subcellular location (Human Protein Atlas): Cytosol; Nucleoplasm
Gene Ontology:
Molecular function: protein binding; ubiquitin protein ligase activity; ubiquitin-protein transferase activity; zinc ion binding
Biological process: neuromuscular junction development; protein ubiquitination
Cellular component: cytosol; cytoplasm; neuromuscular junction; synapse
Genetic constraint (gnomAD): Loss-of-function variants: 19 observed, 47.17 expected, observed/expected ratio (o/e) 0.4, 90% interval 0.28 to 0.59. The synonymous counts are far from expectation, so gnomAD's model fits this gene poorly and the ratio says little. Missense variants: 1,322 observed, 1,108.4 expected, observed/expected ratio (o/e) 1.19, 90% interval 1.14 to 1.25. Synonymous variants: 626 observed, 471.56 expected, observed/expected ratio (o/e) 1.33, 90% interval 1.24 to 1.42.
Homologues: Orthologues: macaque PDZRN3 (99% identical), chimpanzee PDZRN3 (98% identical), mouse Pdzrn3 (95% identical), pig PDZRN3 (94% identical), rat Pdzrn3 (94% identical), dog PDZRN3 (90% identical), rabbit PDZRN3 (85% identical), tropical clawed frog pdzrn3 (77% identical), zebrafish pdzrn3b (72% identical), guinea pig PDZRN3 (67% identical), zebrafish pdzrn3a (48% identical), Drosophila melanogaster Slip1 (17% identical), and 1 more. Paralogues in human: PDZRN4 (57% identical), PDZD4 (36% identical).
Diseases named in the same sentence as PDZRN3 in open-access papers:
PDZRN3 is named in the same sentence as 24 diseases in open-access papers, as found by Europe PMC text mining. Sharing a sentence is not in itself a finding about the gene and the disease. The quoted sentences say what the papers report.
asthma (1 paper, 2021). "LEPN observed in this EWAS is involved in angiogenesis, PTGS1 from isocyanate-asthma research is involved in angiogenesis regulation, and SALL1 and PDZRN3 observed in our GWAS on isocyanate biomarkers are also involved in angiogenesis and vascular morphogenesis, respectively." (PMID 34335698, 2021).
atherosclerosis (1 paper, 2022). A disease characterized by the build-up of fatty material and calcium deposition in the arterial wall resulting in partial or complete occlusion of the arterial lumen. "Nevertheless, the role of CARTPT and PDZRN3 methylation in atherosclerosis has been firstly revealed in our study." (PMID 35915606, 2022). "Although PDZRN3 has been rarely reported in atherosclerosis as far as we know, PDZRN3 has been evidenced to involve in multiple developmental processes, such as vascular morphogenesis, differentiation of myoblasts, and endothelial intercellular junctions." (PMID 35915606, 2022). "Among them, PDZRN3 was significantly highly expressed in atherosclerosis samples compared with nonatherosclerotic samples." (PMID 35915606, 2022). "In GSE20129 dataset, CARTPT, RYR2, CNTN4, PDZRN3, and SLC22A3 all showed differential expression levels in atherosclerosis vs. nonatherosclerotic samples." (PMID 35915606, 2022).
breast carcinoma (1 paper, 2025). "Our results show that the expression of PDZRN3 in breast cancer is low, and its expression is related to the prognosis of patients." (PMID 39781342, 2025). "First, we transfected the PDZRN3 overexpression plasmid into the breast cancer cell line MDA-MB-231 to increase the expression of PDZRN3." (PMID 39781342, 2025). "In addition, both in vitro and in vivo experiments have demonstrated that FBXL6 and PDZRN3 can influence the growth of breast cancer cells." (PMID 39781342, 2025). "Our study found that PDZRN3 had Low expression in breast cancer and inhibited cell progression." (PMID 39781342, 2025). "Finally, in vitro and in vivo experiments validated the effects of FBXL6 and PDZRN3 on breast cancer development." (PMID 39781342, 2025).
cardiac hypertrophy (1 paper, 2022). "We examined Pdzrn3 expression a model of pressure-overload stress of the heart by Angiotensin-II (Ang II) infusion that caused cardiac hypertrophy and lead to heart failure (decompensation phase)." (PMID 34996942, 2022). "The loss of Pdzrn3 may contribute to the mechanism of protecting the heart from transitions from a compensated to a decompensated cardiac hypertrophy in promoting cardiomyocyte elongation." (PMID 34996942, 2022). "Altogether these data indicate that in CM, Pdzrn3 is essential in the transition from concentric to eccentric hypertrophy and subsequent heart failure in models of induced cardiac hypertrophy." (PMID 34996942, 2022).
cardiomyopathy (1 paper, 2022). A disease of the heart muscle or myocardium proper. "When Pdzrn3 postnatal expression was repressed at birth, no signs of cardiomyopathy were detected; cardiac structure, dimension and LVEF were all normal." (PMID 34996942, 2022).
colorectal cancer (1 paper, 2024). A primary or metastatic malignant neoplasm that affects the colon or rectum. "The E3 ubiquitin ligase PDZ Domain Containing Ring Finger 3 (PDZRN3) mediates the ubiquitination and degradation of TBX20 protein in early colorectal cancer tissues." (PMID 38965548, 2024).
heart failure (1 paper, 2022). Inability of the heart to pump blood at an adequate rate to meet tissue metabolic requirements. "We found an increased expression at the transcript and protein levels for Pdzrn3 associated with heart failure, 4 weeks post Ang II treatment." (PMID 34996942, 2022). "We report that cardiomyocyte specific Pdzrn3 deletion, protects the heart from the transition to heart failure, under conditions of pressure overload stress." (PMID 34996942, 2022). "In models of pressure-overload stress heart failure where Pdzrn3 expression is re-induced, CM-specific Pdzrn3 knockout showed complete protection against degradation of heart function." (PMID 34996942, 2022). "In models of pressure-overload stress heart failure, CM-specific Pdzrn3 knockout showed complete protection against degradation of heart function." (PMID 34996942, 2022). "Conversely, PDZRN3 suppression, maintained cardiomyocyte elongation against hypertrophic stress that led to an increase in sphericity (and block heart failure evolution)." (PMID 34996942, 2022). "A moderate CM overexpression of Pdzrn3 (Pdzrn3 OE) during the first week of life, induced a severe eccentric hypertrophic phenotype with heart failure." (PMID 34996942, 2022). "A moderate overexpression of Pdzrn3 (Pdzrn3 OE) during the first week of life, induced a severe eccentric hypertrophic phenotype with heart failure." (PMID 34996942, 2022). "This study identifies PDZRN3 as a novel signaling regulator of polarized myocyte organization and opens this pathway up to the development of novel therapeutic strategies for preventing heart failure pathologies." (PMID 34996942, 2022). "We showed that Pdzrn3 is a critical regulator of CM maturation and stabilization of IDs and plays a major role in the transition from concentric to eccentric hypertrophy toward heart failure." (PMID 34996942, 2022). "Our results reveal a novel signaling pathway that controls a genetic program essential for heart maturation and maintenance of overall geometry, as well as the contractile function of CM, and implicates PDZRN3 as a potential therapeutic target for the prevention of human heart failure." (PMID 34996942, 2022).
sarcoma (1 paper, 2025). A usually aggressive malignant neoplasm of the soft tissue or bone. "Repeat biopsy and next-generation sequencing (NGS) were suggestive of PDZRN3/RAF1 fusion mutated sarcoma." (PMID 40556788, 2025).
soft tissue sarcoma (1 paper, 2020). A malignant neoplasm arising from muscle tissue, adipose tissue, blood vessels, fibrous tissue, or other supportive tissues excluding the bones. "In a previous study, RAF1 fusions were reported in soft tissue sarcoma, in which the fusion counterparts, PDZRN3, SLMAP and TMF1, were identified in three of eight cases." (PMID 32825119, 2020).
tumor (5 papers, 2020 to 2025). "The results showed that over-expression of PDZRN3 significantly inhibited tumor growth." (PMID 39781342, 2025). "Further studies are warranted to determine the role of PDZRN3 in tumor cells." (PMID 31980707, 2020). "It will be of interest to examine whether signaling from PDZRN3 is altered in tumor cells." (PMID 31980707, 2020). "The potential roles of PDZRN3 and ADAMTSL4 in regulating tumor immune microenvironment are worth exploring." (PMID 35087839, 2021). "Among the members of the LNX/PDZRN family, LNX3 (also known as PDZRN3 or SEMCAP3, hereafter referred to as LNX3) has been highlighted in recent years after the discovery of its cellular and pathophysiological roles in various tissues and in tumor development." (PMID 33333989, 2020). "What’s more, E3 ligase PDZ domain containing ring finger 3 (PDZRN3) is reported to mediate K63-linked ubiquitination and degradation of TBX20, a tumor-suppressive protein that impedes Non-homologous End Joining DNA damage repair and suppresses CRC cell proliferation." (PMID 38104139, 2023).
cancer (3 papers, 2020 to 2021). A tumor composed of atypical neoplastic, often pleomorphic cells that invade other tissues.
heart disease (1 paper, 2022). "To understand the function of Pdzrn3 induction in cardiac disease, we analyzed myocardial expression patterns of PDZRN3 during embryogenesis and in postnatal weeks." (PMID 34996942, 2022).
neurodegenerative disease (1 paper, 2022). A disorder of the central nervous system characterized by gradual and progressive loss of neural tissue and neurologic function. "Additionally, PDZRN3 and PPP3CB genes are associated with neurodegenerative diseases, as reported in87,88." (PMID 35705654, 2022).
PDZRN3 also shares sentences with these, for which no sentence is quoted: cervical carcinoma (1 paper); coloboma (1); craniosynostosis (1); head and neck tumour (1); hypertrophy (1); infection (1); neutropenia (1); Obesity (1); ovarian carcinoma (1); renal cell carcinoma (1); Robinow syndrome (1).